DDR1 (discoidin domain receptor tyrosine kinase 1)
Diseases named in the same sentence as DDR1 in open-access papers (continued):
Sharing a sentence is not in itself a finding about the gene and the disease.
pancreatic cancer (continued). "Furthermore, preclinical studies in a pancreatic cancer model reveal that targeting DDR1 not only disrupts collagen architecture but also enhances chemotherapeutic efficacy and promotes immune cell infiltration." (PMID 40869052, 2025). "In pancreatic cancer, blocking the collagen/DDR1-based signaling pathway inhibits tumor growth; however, its effect on autophagy remains unknown." (PMID 38071340, 2023). "Subsequently, TM4SF1 promoted pancreatic cancer metastasis by regulating DDR1 expression." (PMID 36871072, 2023). "However, very recently, Nature published an article in which fibrosis inhibited malignant transformation, and activation of DDR1 signaling by collagen degradation products correlated with poor prognosis in pancreatic cancer." (PMID 36613638, 2022). "DDR1-induced NET formation enhances pancreatic cancer cell invasion." (PMID 34237033, 2021). "In addition, collagen-DDR1 signaling can induce an invasive phenotype in pancreatic cancer cells through an epithelial-mesenchymal transition (EMT)." (PMID 34237033, 2021). "Compound 51 also inhibited DDR1-mediated cadherin switching, suppressed colony development of pancreatic cancer cells, exhibited good PK properties, and displayed a promising therapeutic activity through oral administration in orthotropic syngeneic pancreatic cancer models." (PMID 34207360, 2021). "We reported in an earlier study that the pharmacological inhibition of DDR1 activation by a novel small-molecule inhibitor, 7rh benzamide, inhibited tumorigenesis and enhanced chemosensitivity in orthotopic xenografts and autochthonous pancreatic tumors." (PMID 34237033, 2021). "This review outlines additional mechanisms by which HCK, ABL2, and DDR1 may play a role in pancreatic cancer and fibrosis." (PMID 33233470, 2020). "This study also outlines additional mechanisms by which HCK, ABL2, and DDR1 may play a role in pancreatic cancer and fibrosis." (PMID 33213062, 2020). "To examine whether TM4SF1 regulated DDR1 expression in pancreatic cancer cell lines, we transfected siRNA into cells and found that the down-regulation of TM4SF1 could decrease the mRNA and protein expression levels of DDR1 in PANC-1 and AsPC-1." (PMID 28368050, 2017). "Therefore, further studies in our laboratory will be focused on the function of TM4SF1, DDR1 and integrins in pancreatic cancer cells contacting with collagen." (PMID 28368050, 2017). "Our hypothesis was based on earlier observations, by others, which showed that simultaneous interactions of DDR1 and α2β1 integrin with COLI, cause upregulation of N-Cad and cell scattering (EMT) in pancreatic cancer cells." (PMID 23991074, 2013). "In pancreatic cancer cells, on the other hand, cooperation of both DDR1 and α2β1 is required to mediate collagen-induced epithelial-to-mesenchymal transition, to transmit a signal to JNK, which in turn up-regulates N-cadherin expression and promotes cell scattering." (PMID 23284937, 2012). "Cooperation of DDR1 and α2β1 was required in the regulation of cell scattering in pancreatic cancer cells or the self-renewal of mouse embryonic stem cells, whereas in MDCK cells, DDR1 was shown to inhibit several α2β1-mediated cell functions including cell adhesion and migration." (PMID 23284937, 2012). "The interplay of the two factors was also further suggested by the fact that the growth-promoting impact of the COLα1 (I) on pancreatic cancer cells could be inhibited following the addition of DDR1 inhibitors or in the presence of cleavage-resistant COLα1 (I)." (PMID 37373151, 2023). "Thus, we hypothesized that TM4SF1 might collaborate with DDR1 involved in the formation of invadopodia which had the ability to degrade ECM to regulate pancreatic cancer metastasis." (PMID 28368050, 2017). "The DDR1/PYK2/ERK signaling cascade activated by collagen also enhances autophagy flux and cell proliferation in pancreatic cancer cells." (PMID 40563472, 2025).
pancreatic cancer (continued). "In pancreatic cancer, type VIII collagen activates PI3K-AKT and NF-κB signaling via DDR1, contributing to drug resistance." (PMID 40563472, 2025). "In the case of pancreatic cancer cells, cooperative activation of FAK and pyk2 via integrin β1 and DDR1, respectively is an important EMT-inducing pathway." (PMID 36613638, 2022). "In pancreatic cancer, a novel pathway including TM4SF1/DDR1/MMP2 and 9 enhances invadosome formation and activity, thereby enhancing cell migration and invasion capabilities." (PMID 33917302, 2021). "Collagen-induced DDR1 activation and epithelial–mesenchymal transition can be attenuated by the DDR1 inhibitor 7f which disrupts DDR1-PYK2-PEAK signaling in pancreatic cancer." (PMID 33233470, 2020). "We next investigated the role of TM4SF1 and its relationship with DDR1 in pancreatic cancer tissues, we measured the mRNA expression levels of TM4SF1 and DDR1 in 20 pairs of pancreatic cancer tissue samples." (PMID 28368050, 2017). "In pancreatic cancer tissues, qRT-PCR and scatter plots analysis further determined that TM4SF1 had a correlation with DDR1." (PMID 28368050, 2017). "Our study investigated that when overexpressed DDR1 in TM4SF1-silenced cells, the number of pancreatic cancer cells with invadopodia and the expression of MMP2 and MMP9 were increased." (PMID 28368050, 2017). "Collectively, our study provides a novel regulatory pathway involving TM4SF1, DDR1, MMP2 and MMP9, which promotes the formation and function of invadopodia to support cell migration and invasion in pancreatic cancer." (PMID 28368050, 2017). "DDR1 activation via cleaved collagen I binding triggered NF-κB-NRF2 signaling to enhance macropinocytosis and mitochondrial biogenesis, fostering tumor progression in pancreatic cancer models." (PMID 40993737, 2025). "In pancreatic cancer, TM4SF1-induced migration and invasion require DDR1." (PMID 33917302, 2021). "Compound design was guided by the comparison of predicted binding modes in DDR1 to those in an off-target kinase TrkC followed by the comparison between DDR1 and a homology model of DDR2, and the compounds were effective against in vivo orthotopic mouse models of pancreatic cancer." (PMID 34827669, 2021).
prostate carcinoma (29 papers, 2014 to 2025). A carcinoma that arises from epithelial cells of the prostate gland. "DDR1 expression is one of twelve genes identified in a study to be associated with HNF1 homeobox B (HNF1b) mediated prostate cancer risk." (PMID 32492656, 2020). "For instance, upregulated DDR1 expression promotes cancer development by enhancing cancer cell survival and invasion, and high DDR1 expression is associated with short hormone resistance interval in prostate carcinoma." (PMID 25978031, 2015). "Recently, low levels of DDR1 have been associated with a poor prognosis in prostate cancer." (PMID 32492656, 2020). "In cancer research, overexpression of miR-199b-5p can inhibit the proliferation, migration, and invasion of prostate cancer cells in vitro and tumor growth and metastasis in vivo by targeting DDR1." (PMID 38770735, 2024). "For instance, in prostate cancer, DDR1 activates Pyk2 and MKK7 (Mitogen-activated protein kinase kinase 7), resulting in increased expression of the mesenchymal markers vimentin and N-cadherin and decreased expression of the epithelial marker E-cadherin." (PMID 33917302, 2021). "Here, we examined the expression of DDR1 in prostate cancer (PCa), and assessed its potential value as a prognostic marker, as a function of grade, stage and other clinicopathologic parameters." (PMID 34548097, 2021). "PCA-1 increased prostate cancer cell invasion through DDR1 and MMP9 expression in a chick chorioallantoic membrane (CAM) assay." (PMID 33917302, 2021). "DDR1 has been shown to have effects on various molecules involved in prostate cancer metastasis such as MMPs." (PMID 32492656, 2020). "Upregulation of DDR1 in multiple human cancers including lung, breast, colon, esophagus, brain, ovary and prostate cancers implies that DDR1 is involved in tumor progression." (PMID 25369402, 2014). "In BC and prostate cancer cell lines, DDR1 activated proliferation." (PMID 40105492, 2025). "DDR1 increased the chemosensitivity of prostate cancer cells." (PMID 32492656, 2020). "Ddr1 has been reported to affect intracellular signaling through the AKT and ERK pathways in prostate cancer cells." (PMID 37373466, 2023). "Accordingly, DDR1 activates EMT via stimulating the protein expression of N-cadherin and vimentin and phosphorylation of Pyk2 and MKK7 in prostate cancer." (PMID 35267698, 2022). "In prostate cancer, prostate cancer antigen 1 (PCA-1) increases the level of DDR1 and Bcl-xl, an antiapoptotic molecule, resulting in the inhibition of apoptosis." (PMID 33917302, 2021). "It has reported that E2F1 could promote invasion and migration of prostate cancer and osteosarcoma cells through regulating CD147 and DDR1 expression." (PMID 31801947, 2019).
ovarian cancer (27 papers, 2011 to 2025). A primary or metastatic malignant neoplasm involving the ovary. "In contrast, elevated DDR1 expression appeared to be associated with favorable prognosis in ovarian cancer." (PMID 40869052, 2025). "Elevated DDR1 levels in high-grade and advanced ovarian cancers has been implicated with poor survival." (PMID 34837026, 2021). "Delving deeper to understand the underlying molecular mechanisms involved in ovarian cancer pathogenesis, we identified an inverse correlation of miR-199a-5p with DDR1, a collagen receptor with receptor tyrosine kinase activity." (PMID 34837026, 2021). "In the present study, loss of miR-199a-3p was found to cause the ectopic high expression of DDR1 in ovarian cancer." (PMID 28743276, 2017). "Hypermethylation mediated silence of miR-199a-3p is confirmed to promote DDR1 expression, which is associated with a poor prognosis in patients with ovarian cancer." (PMID 28743276, 2017). "In line with this, we found that the expression of miR-199a-3p significantly increased while DDR1 were intensively downregulated after 5-Aza-dC addition, suggesting a hypermethylation mediated loss of miR-199a-3p in ovarian cancer." (PMID 28743276, 2017). "The association between DDR1 expression, tumor grade, clinical disease stage, and patient outcome suggests an in vivo role for this signal transduction pathway in ovarian cancer." (PMID 21541037, 2011). "In the present study, we showed that DDR1 expression was associated with high-grade and advanced stage tumors, as well as with poor survival in patients with ovarian cancer." (PMID 21541037, 2011). "However, there was not such a concordant and significant association between the DDR1 expression and the prognosis in breast and ovarian cancer patients." (PMID 35935941, 2022). "DDR1-IN-1 increased cell sensitivity to cisplatin, synergized with cisplatin to suppress the invasive ability and oncogenic potential of ovarian cancer cells, and decreased tumor formation in mouse xenografts." (PMID 40603853, 2025). "In the following sections we summarize some of the key breast and ovarian cancer focused research characterizing DDR1 and DDR2 dysregulation." (PMID 34805157, 2021). "Transcriptome and miRNA analysis of these samples corroborated the high DDR1 and low miR-199a-5p expression, establishing the anti-correlative pattern of DDR1 and miR-199a-5p in ovarian cancers." (PMID 34837026, 2021). "We report the inverse correlation of miR-199a-5p: DDR1 in ovarian cancers confirmed with patient cohort analysis." (PMID 34837026, 2021). "We established DDR1 to be a direct target of miR-199a-5p and that ST09-induced DDR1 loss in these ovarian cancer cells resulted in the inactivation of its downstream MMP activation, migration, EMT, and prosurvival NF-κB pathway." (PMID 34837026, 2021). "In this study, both ST09 treated ovarian cancer cell lines showed downregulation of MMP1, MMP2, and MMP9 with DDR1 loss." (PMID 34837026, 2021). "Taken together, these results indicate that miR-199a-5p directly binds to 3’UTR of DDR1 mRNA, decreasing its expression and in ST09 treated ovarian cancer cell lines, miR-199a-5p mediates the downregulation of DDR1." (PMID 34837026, 2021). "The miRNA-transcriptome profiling in these ovarian cancer cell lines treated with the ST09 drug indicated the miR-199a-5p/DDR1 axis to be involved in tumor-suppressive functions." (PMID 34837026, 2021). "Taken together, these results indicate that ST09 induced DDR1 downregulation along with its downstream targets confers an anti-invasive and anti-metastatic characteristic in the ovarian cancer cell lines PA1 and A2780." (PMID 34837026, 2021). "In ovarian cancer tissues, expression of DDR1 is negatively correlated with the expression of miR-199a-3p, where miR-199a-3p inhibits DDR1 overexpression, drastically reducing the migration, invasiveness, and tumorigenicity of ovarian cancer cells." (PMID 34805157, 2021).
ovarian cancer (continued). "The luciferase reporter assay confirmed DDR1 as a direct target of miR-199a-5p in both ST09 treated ovarian cancer cells." (PMID 34837026, 2021). "The ST09 treatment in ovarian cancer cell lines resulted in the deregulation of the miR-199a-5p/DDR1 axis, conferring tumor-suppressive functions." (PMID 34837026, 2021). "It has been shown that DDR1 (protein) is highly expressed in serous ovarian cancers compared to normal ovarian epidermal tissues, with DDR1 mainly expressed in epithelial ovarian cancer (EOC) cells." (PMID 34805157, 2021). "DDR1 has been suggested to serve as potential biomarker for advanced ovarian cancer and has been related to increased cisplatin resistance in those cancer cells." (PMID 33287446, 2020). "Overexpressed DDR1 was previously documented as a common survival driver for a panel of cancer cell lines derived from breast, pancreatic, and ovarian cancers." (PMID 32244515, 2020). "Although a recent study reported on an inverse relation of DDR1 expression and cisplatin sensitivity in ovarian cancer, a potential role of DDR1 in CAM-DR of W1CR cells remains a matter of further investigations." (PMID 31779287, 2019). "Ectopic low levels of miR-199a-3p accompanied with increased DDR1 expressions are detected in ovarian cancer cells or tissues." (PMID 28743276, 2017). "Taken together, miR-199a-3p decreases the expression of DDR1 by directly targeting the 3’UTR of DDR1 mRNA in ovarian cancer cells." (PMID 28743276, 2017). "In summary, our findings highlight a miR-199a-3p/DDR1 pathway, the dysregulation of which leads to the migration, invasion, and chemoresistance of ovarian cancer." (PMID 28743276, 2017). "Aberrant expression of DDR1 was detected in several human cancers including ovarian cancer, which had been shown to increase the migration and invasion of tumor cells." (PMID 28743276, 2017). "In this study, miR-199a-3p is revealed as an upstream regulator of DDR1 which confers the malignance and cisplatin resistance of ovarian cancer." (PMID 28743276, 2017). "Overactivation of miR-199a-3p/DDR1 pathway was observed in the clinical specimens of ovarian cancer, as described by highly expressed miR-199a-3p and DDR1." (PMID 28743276, 2017). "Consistent with the upregulation of DDR1 in other cancer types, both the mRNA and protein of DDR1 were aberrantly overexpressed in ovarian cancer tissues compared with the normal control." (PMID 28743276, 2017). "As expected, the hypermethylation was closely related with decreased miR-199a-3p and upregulation of DDR1 in the ovarian cancer specimens." (PMID 28743276, 2017). "Phenotype experiments showed that overexpression of miR-199a-3p significantly impaired the migratory, invasive, and tumorigenic capabilities of ovarian cancer cells as well as enhanced cisplatin resistance through inhibiting DDR1 expression." (PMID 28743276, 2017). "In the present study, deregulation of Discoidin Domain Receptor 1 (DDR1) in ovarian cancer was found to enhance the resistance to cisplatin." (PMID 28743276, 2017). "Below, we discovered DDR1 as a target of miR-199a-3p, a tumor-suppressor miRNA, which was silenced by hypermethylation in ovarian cancer." (PMID 28743276, 2017). "Consistently, miR-199a-3p inhibitor was found to promote the tumorigenicity of ovarian cancer cells, however, which was disrupted by DDR1 knockdown." (PMID 28743276, 2017). "In the previous reports, overexpression of DDR1 was shown in ovarian cancer and identified as a potential marker for high-grade ovarian cancer." (PMID 28743276, 2017). "Previously studies have identified DDR1 is overexpressed in various human invasive tumors including lung, breast, hepatic, and ovary cancers, highlighting its possible role in tumor initiation, maintenance or progression." (PMID 26297342, 2015). "Hereby, GAS6 is roughly in the middle of this top candidate group, where also well-known ovarian cancer markers like HE4 (WFDC2) or DDR1 are listed." (PMID 23878800, 2013).